PIR (pirin)
Description:
Transcriptional coregulator of NF-kappa-B which facilitates binding of NF-kappa-B proteins to target kappa-B genes in a redox-state-dependent manner. May be required for efficient terminal myeloid maturation of hematopoietic cells. Has quercetin 2,3-dioxygenase activity (in vitro).
Tractability: Small molecule: a structure with a bound ligand is known; a high-quality ligand is known; it has a high-quality binding pocket. PROTAC: it is named in the literature on targeted protein degradation; ubiquitination databases record sites on it; a small molecule that binds it is known.
Target class: Enzyme; Oxidoreductase
Chemical probes: CCT251236 (high quality), PD134649, PD134650
Gene: Protein-coding gene on chromosome X (15,384,799 to 15,493,635, reverse strand). Ensembl gene ENSG00000087842.
Subcellular location: Nucleus; Cytoplasm
Subcellular location (Human Protein Atlas): Nucleoplasm; Cytosol; Nuclear bodies
Pathways (Reactome):
Digestion and absorption: Digestion
Gene Ontology:
Molecular function: metal ion binding; protein binding; quercetin 2,3-dioxygenase activity; transcription coregulator activity
Biological process: monocyte differentiation; digestion; transcription by RNA polymerase II; myeloid cell differentiation
Cellular component: cytoplasm; cytosol; nuclear body; nucleoplasm; nucleus
Homologues: Orthologues: chimpanzee PIR (99% identical), macaque PIR (99% identical), guinea pig PIR (97% identical), dog PIR (96% identical), mouse Pir (96% identical), rat Pir (96% identical), pig PIR (92% identical), rabbit PIR (87% identical), tropical clawed frog pir (77% identical), zebrafish pir (71% identical).
Diseases named in the same sentence as PIR in open-access papers:
PIR is named in the same sentence as 112 diseases in open-access papers, as found by Europe PMC text mining. Sharing a sentence is not in itself a finding about the gene and the disease. The quoted sentences say what the papers report.
breast cancer (35 papers, 2013 to 2025). A primary or metastatic malignant neoplasm involving the breast. "Herein, we demonstrated the oncogenic function of piR-823 in association with the luminal subtype of breast cancer by regulating breast CSCs." (PMID 33791297, 2021). "In the present study, we have identified piR-36,712 as a tumor suppressor that is downregulated in breast cancer and revealed the possible underlying mechanism for the action of piR-36,712 as a tumor suppressor RNA." (PMID 30636640, 2019). "Also, upregulation of piR-4987 expression was linked with lymph node positivity resulting in poorer outcome in breast cancer patients." (PMID 32211149, 2020). "Furthermore, deleterious mutations in the PIR gene were recently identified in breast cancers that could affect protein structure, stability and function." (PMID 37308689, 2023). "In this study, we profiled piRNA expression in 96 primary breast cancer tissues and explored the prognostic and functional significance of piR-775." (PMID 41189020, 2025). "Conversely, the expression of piR-23662, piR-26526, piR-26527, piR-26528, piR-30293, piR-34377, piR-34736, piR-35407, piR-36318, and piR-36249 is significantly reduced in breast cancer cells." (PMID 39795985, 2024). "An analysis of these piRNAs in the literature and in specific databases returned only piR-hsa-7193, which we found strongly down-regulated (log2(FC)= −4.4), and it is known to be highly up-regulated in breast cancer patients." (PMID 38534323, 2024). "Senescent neutrophil exosomes can transfer chemoresistance and EMT characteristics to recipient breast cancer cells through cell-to-cell transfer of piR-17560." (PMID 38667297, 2024). "In breast cancer, piR-651, piR-823 and piR-021285 is highly expressed compared with normal breast tissue." (PMID 36882835, 2023). "Pirin also interacts with breast cancer anti-estrogen resistance 1 (BCAR1) protein that activates RAC1." (PMID 38033031, 2023). "Enforced overexpression of piR-2158 in basal-like or luminal subtypes of breast cancer cells suppressed cell proliferation, migration, epithelial-mesenchymal transition (EMT) and stemness in vitro." (PMID 37153732, 2023). "Over-expression of PIR in breast cancer cells play roles in tumorigenesis and cancer progression through induction of the E2F1 pathway." (PMID 38033031, 2023). "In breast cancer stem cells, piR-932 and PIWIL2 formed a complex to promote CpG island methylation of the Latexin promoter region and reduced its expression." (PMID 36212439, 2022). "For instance, lentiviral vector-mediated overexpression of piR-36712 in breast cancer cells suppressed malignant phenotypes and had a synergistic anti-tumor effect when combined with chemotherapy agents." (PMID 35155584, 2022). "piR-36712 suppresses breast cancer cell proliferation, invasion, and migration by combining with SEPW1P RNA." (PMID 34249688, 2021). "Nine pairs of clinical tissue samples (tumor and matched normal samples from the same patient) of luminal breast cancer were applied for piR-823 analysis, further indicating the upregulation of piR-823 in the tumors compared to normal tissues." (PMID 33791297, 2021). "Pirin is reported as a biomarker in breast cancer, which is abnormal and irregular proliferation of cells associated with inappropriate stimulation of pathways involved in signal transduction." (PMID 34262943, 2021). "Further analysis indicated the correlation of piR-016658 and piR-016975 with breast cancer cell stemness." (PMID 34295823, 2021). "Overexpression of piR-35127 and piR-46545 and knockdown of piR-34871 and piR-52200 significantly reduced cell proliferation in both lung cancer cell lines (A549 and H1299) and breast cancer cell lines (Hs578T and MDA-MB-231)." (PMID 34295823, 2021). "The results indicated that four out of six piRNAs were up-regulated in breast cancer tissue including piR-4987, piR-20365, piR-20485, and piR-20582." (PMID 32211149, 2020).
breast cancer (continued). "As such, piR-34871 and piR-52200 were knocked down in normal lung and breast epithelial cells and lung and breast cancer cells." (PMID 28423657, 2017). "Deep sequencing and RT-PCR of breast cancer tumours and matched normal tissue samples found four significantly upregulated piRNAs: piR-4987, piR-20365, piR-20485, piR-20582." (PMID 26768585, 2016). "After hormone treatment, while piR-651 expression had increased both breast and prostate cancer cell lines, piR-823 expressions increased in prostate cancer cell lines and only in the breast cancer cell line which was malignant." (PMID 27414029, 2016). "While it was observed that the expression of piR-651 and piR-823 increased upon administration, only the piR-823 expression was detected to have decreased in the estrogen-dependent breast cancer cell line MCF-7." (PMID 27414029, 2016). "Additionally, earlier studies showed that piR-34736, piR-35407, piR-36249, piR-34377, and piR-36318 are typically downregulated, while piR-651, piR-36026, piR-20582, piR-932, piR-36743, piR-021285, and piR-31106 are upregulated in breast cancer." (PMID 40002172, 2025). "Moreover, two types of transgenic mouse models of PyMT- or Wnt-induced breast cancer further confirmed downregulation of piR-2158 in breast cancer tumors." (PMID 37153732, 2023). "We found that piR-2158 was downregulated independently of the ER status in human breast cancer." (PMID 37153732, 2023). "Our current study confirmed downregulation of piR-2158 in breast cancer." (PMID 37153732, 2023). "Additionally, it was revealed that SNP rs1326306 G > T in piR-021285 increased the likelihood of breast cancer (BC)." (PMID 37296747, 2023). "In breast cancer, the levels of piR-4987 are positively correlated with lymph node metastasis." (PMID 35155584, 2022). "Complex formed by piRNAs binding to Piwi proteins, such as piR-651/Piwil 1 in gastric cancer, piR-54265/Piwil 2 in colorectal cancer, piR-932/Piwil 2 in breast cancer, have been demonstrated to regulate cell proliferation, invasion and metastasis of cancer cells." (PMID 34295823, 2021). "In addition to piR-021285 and piR-823, piR-932 also showed overexpression in human breast cancer, playing tumor-promoting roles through epigenetic mechanism." (PMID 34295823, 2021). "In addition, piR-36712 showed involvement in chemo-sensitivity of breast cancer cells in response to paclitaxel or doxorubicin." (PMID 34295823, 2021). "Furthermore, PIR knockdown resulted in a noticeably reduced cell proliferation rate in breast cancer cells and decreased xenograft tumor growth in mice." (PMID 33557375, 2021). "In Piwil2 positive breast cancer stem cells, piR-932 could bind with Piwil2 to suppress the expression of Latexin by promoting methylation of the CpG island at its promoter region." (PMID 34295823, 2021). "Recently, it has been identified that PIR positively regulates breast cancer cell proliferation, xenograft tumor formation, and metastasis, through an enforced transition of G1/S phase of the cell cycle by upregulation of E2F1 expression at the transcriptional level." (PMID 34262943, 2021). "Those aberrantly expressed piRNAs in breast cancer including piR-4987, piR-021285, piR-823, piR-932, piR-36712, piR-016658 and piR-016975 may held potential to be developed as biomarkers and/or therapeutic targets in breast cancer." (PMID 34295823, 2021). "Since piR-36,712 is substantially downregulated in breast cancer, we wanted to know whether it has effect on breast cancer cell phenotypes." (PMID 30636640, 2019). "Interestingly, four of the top-five upregulated piRNAs previously identified in breast cancer growing cells, were found downregulated in the SH cells (piR-31636, piR-57125, piR-35548 and piR-57125)." (PMID 29963267, 2018).
breast cancer (continued). "Meanwhile, although piR-34736 was found to be underexpressed in breast cancers and lnc-JPH1-7 was also identified in esophageal (ESCCAL-1) and lung (LCAL80) squamous cell carcinomas, their clinical and molecular significance has, up to now, remained uninvestigated." (PMID 27323410, 2016). "In conclusion, the current study not only reveals a novel mechanism through which piR-2158 inhibits mammary gland tumorigenesis via regulating cancer stem cells and tumor angiogenesis, but also provides a novel therapeutic strategy in treatment of breast cancer." (PMID 37153732, 2023). "However, the regulatory function and mechanisms of piR-2158 in breast cancer remain unclear until our current study demonstrating piR-2158 inhibition of breast cancer by targeting IL11-STAT3 signaling." (PMID 37153732, 2023). "Finally, piR-34736 (DQ596670), upregulated by 2-fold in TCGA HNSCCs and correlated to patient survival and PRDM9 mutation, was recently observed to be downregulated in breast cancers, with uncharacterized functional significance." (PMID 27323410, 2016). "The current study reveals a novel regulatory mechanism through which piR-2158 involved in the interaction between AP-1 transcriptional complex and the promoter of IL11 in human breast cancer cells." (PMID 37153732, 2023). "In fact, Pirin binds to the 3′-terminal region of the E2F1 promoter and subsequently facilitates G1 to S phase transition in breast cancer cells." (PMID 33557375, 2021). "In the present study, we investigated the clinical significance of the candidate biomarkers GGH FAAH, PIR and TAF5L in predicting breast cancer progression." (PMID 23374458, 2013). "Herein, we identified downregulation of piR-2158 in human breast cancer tumors, especially in ALDH+ breast cancer stem cells (BCSCs) from patients and cell lines, which was further validated in two types of genetically engineered mouse models of breast cancer (MMTV-Wnt and MMTV-PyMT)." (PMID 37153732, 2023). "In contrast, lower levels of piR-016975 were determined not only in basal-like subtype of breast cancer cells compared to luminal subtype, but also in breast cancer stem cells compared to non-stem breast cancer cells." (PMID 34295823, 2021). "PIWIL2 was found to be significantly overexpressed in breast cancer stem cells, inducing epithelial-to-mesenchymal transition (EMT) following TGF-β1 treatment, and PIWIL2 also formed a complex with one of three significantly overexpressed piRNAs, piR-932." (PMID 26768585, 2016). "We found that IL1R1 (Il1r1 interleukin 1 receptor, type I), BCAR3 (breast cancer anti-estrogen resistance 3), KCNH2 (potassium channel, voltage gated related subfamily H, member 2), PIR (pirin), and ZDHHC23 (zinc finger, DHHC-type containing 23) were differentially expressed." (PMID 27536776, 2016). "Additionally, the piRNAs, including piR-4987, piR-20365, piR-20485, and piR-20582, were found to be upregulated in samples from breast cancer patients when compared to matched non-tumor tissues." (PMID 39795985, 2024). "However, piR-823 has been shown to inhibit gastric carcinogenesis and induces the expression of stem cell markers (including OCT4, SOX2, KLF4, NANOG, and hTERT) and increases the formation of mammospheres, as has been demonstrated on breast cancer MCF-7 and T-47D cells." (PMID 38667297, 2024). "Additionally, piR-36743 and its expression in serum could not distinguish healthy controls from patients with breast cancer." (PMID 37296747, 2023).
colorectal cancer (24 papers, 2014 to 2026). A primary or metastatic malignant neoplasm that affects the colon or rectum. "Based on their aberrant overexpression, several piRNAs have been dubbed as potential early diagnostic markers for colorectal cancer from serum or tissues, piR-24000, piR-020619, piR-020450, piR-54265." (PMID 38003403, 2023). "We aimed to investigate the expression levels of piR-823 in both serum and tissues of colorectal cancer patients and the ability to use its serum level as a non-invasive diagnostic biomarker to detect colorectal cancer." (PMID 33921704, 2021). "In our study TPhA decreased the viability of pirin-proficient and pirin-deficient colorectal cancer cells equally well, strongly suggesting that this compound has additional targets and supporting the need for the identification and development of more specific pirin inhibitors." (PMID 35204145, 2022). "Indeed, pirin has recently been implicated as an inhibitor of apoptosis in colorectal cancer cells." (PMID 39917624, 2025). "In colorectal cancer, piR-823 fosters invasion by stabilizing HIF-1α and G6PD, correlating with poor prognosis." (PMID 42022287, 2026). "Upregulated pirin (PIR) facilitates colorectal cancer (CRC) survival by suppressing Fas‐mediated apoptosis in two ways, namely, the disruption of NFκB2‐driven FAS transcription and the attenuation of FAS membrane translocation and assembling." (PMID 38148593, 2024). "Dysregulation of Pirin has been reported to play a role in various tumorigenesis pathways and cancers such as melanoma and colorectal cancer for instance." (PMID 39414818, 2024). "Serum piR-020619 and piR-020450 show strong potential as colorectal cancer-specific biomarkers for early detection." (PMID 37941038, 2023). "Here we found that pirin is overexpressed in human colorectal cancer in comparison with matched normal tissue." (PMID 35204145, 2022). "The overexpression of pirin in human colorectal cancer correlated with the overexpression of Nrf2 and the classical Nrf2 target gene, NQO1, suggesting that increased transcription of both PIR and NQO1 is a consequence of Nrf2 activation." (PMID 35204145, 2022). "Sulforaphane treatment also increased (by 1.6-fold) the mRNA levels for pirin in the colorectal cancer cell line Caco2." (PMID 35204145, 2022). "Our study extends the current knowledge by showing that pirin is overexpressed in human colorectal cancer in comparison with matched control tissue." (PMID 35204145, 2022). "Understanding the functional consequences of the observed pirin upregulation in colorectal cancer requires further investigation." (PMID 35204145, 2022). "We first compared the mRNA levels for pirin in the human colorectal cancer cell line DLD1 (Nrf2-WT) as well as Nrf2-knockout (Nrf2-KO) and Nrf2-gain-of-function (Nrf2-GoF) mutant isogenic lines that had been generated using CRISPR/Cas9 genome editing." (PMID 35204145, 2022). "For example, piR-54265 is a molecular marker for early colorectal cancer screening in the general population." (PMID 34118972, 2021). "In colorectal cancer, piR-823 was reported to promote cell proliferation and tumorigenesis by upregulating phosphorylation and transcriptional activity of HSF1." (PMID 33791297, 2021). "One recent study has showed that serum piR‐020619 and piR‐020450 are promising novel biomarkers for early detection of colorectal cancer." (PMID 33169519, 2020). "Serum piR‐020619 and piR‐020450 are promising novel biomarkers for early detection of colorectal cancer." (PMID 33169519, 2020). "To further validate our in vitro results that piR-1245 regulated those tumor suppressors, we investigated the expression correlation between piR-1245 and its target genes in colorectal cancer tissues." (PMID 29382334, 2018). "The importance of the cellular functions of pirin is highlighted by the fact that changes in pirin expression were observed in several human cancers including acute myeloid leukemia, melanoma, and colorectal carcinoma." (PMID 24390086, 2014).
colorectal cancer (continued). "Interestingly, pirin has recently been shown to contribute to anti-apoptotic effects in colorectal cancer." (PMID 39917624, 2025). "Pirin is overexpressed in various types of cancer, such as colorectal cancer and melanoma." (PMID 36901722, 2023). "Thus, using genetic and pharmacologic approaches, we have demonstrated that pirin is a transcriptional target of Nrf2 in human colorectal cancer cells, mouse intestinal organoid cultures and in vivo in the murine colon." (PMID 35204145, 2022). "Furthermore, piR-19521, piR-18849, and piR-1245 also show novel independent prognostic characteristics and have the potential to be used as prognostic markers in colorectal cancer." (PMID 34118972, 2021). "Additionally, serum piR-54265, piR-020619, and piR-020450 were also found to serve as sensitive and specific noninvasive biomarkers for early colorectal cancer detection in previous studies." (PMID 34118972, 2021). "In addition, piR-823 downregulation suppressed cell proliferation of colorectal cancer cells by a direct modulation of the transcriptional activity of HSF1." (PMID 32357464, 2020). "PIR was significantly upregulated in CRC as compared with corresponding normal tissues according to public TCGA and GEO database, while FAS is downregulated in colorectal cancer." (PMID 38148593, 2024). "Thus, first we asked whether pirin affects the viability of DLD1 colorectal cancer cells using two approaches: (i) pharmacological, by treatment with triphenyl compound A (TPhA), a small molecule inhibitor of pirin, and (ii) genetic, by knockdown of pirin using siRNA." (PMID 35204145, 2022). "The depletion of pirin in the human colorectal cancer cell line DLD1 does not affect cell viability or migration." (PMID 35204145, 2022). "Our functional studies show that pirin depletion does not affect the viability or migration of DLD1 colorectal cancer cells, and thus the functional significance of pirin overexpression in colorectal cancer requires further investigation." (PMID 35204145, 2022). "The small molecule pirin inhibitor TPhA decreased the viability of human colorectal cancer (DLD1) cells, but this decrease was independent of the levels of pirin." (PMID 35204145, 2022).